CD163 (CD163 molecule)
Diseases named in the same sentence as CD163 in open-access papers (continued):
Sharing a sentence is not in itself a finding about the gene and the disease.
tumor (continued). "While CD68 and CD163 are widely used surrogate markers to investigate macrophage polarity and characterize tumor-associated macrophages, the binary classification of macrophages into M1 and M2 polarized activation states is overly simplistic." (PMID 39456610, 2024). "In solid tumors, such as those of the breast and pancreas, infiltrating Cluster of differentiation 68 (CD68)+ or Cluster of differentiation 163 (CD163)+ tumor-associated macrophages are correlated with poor outcomes and immunosuppression." (PMID 39055564, 2024). "This was also corroborated by IMC results where tumors presented lower frequencies of cells expressing macrophage markers like CD68, F4/80 as well as suppressive tumor associated macrophage markers like CD163 and CD206." (PMID 38206570, 2024). "Under homoeostasis, CD163 scavenges haptoglobin–haemoglobin complexes, and in cancer, CD163 is a widely known marker for tumour-promoting M2-like macrophages, generally associated with poor prognosis." (PMID 38831013, 2024). "One BRIT tumor sample showed high γH2AX activity, STING activation, CD8+ T-cell infiltration, CD4+ T-cell infiltration, and strong CD163+ tumor-associated macrophage populations." (PMID 39669575, 2024). "TREM2, FOLR2, and CD163 are all markers found on tumor-associated M2 macrophages in adult cancer and have been shown to suppress the immune response and promote tumor growth." (PMID 38358826, 2024). "A previous study found that CD163/FKBP51s cells in the PB increased following incomplete tumor resection, suggesting that tumor persistence associated with disruption of the blood-brain barrier promotes the release of these TAMs into circulation." (PMID 38651817, 2024). "M2 CD163-positive tumor-associated macrophages (TAMs) were shown to be implicated in DLBCL disease activity regulation." (PMID 38474108, 2024). "SPP1-expressing TAM subpopulations have been shown to promote intravasation and metastasis in HNSCC and low TAM containing tumours (CD68 CD163) have been associated with better survival." (PMID 38803348, 2024). "In this study, we demonstrate that CD14− cDC2s can directly convert to CD1c+CD14+CD163+ DCs driven by tumor-associated factors." (PMID 38242119, 2024). "MACC1mRNA levels were found to be positively correlated with CD163+ tumor-associated macrophages and negatively correlated with CD56+ natural killer cells and CD8+ cytotoxic T cells." (PMID 36979146, 2023). "This meta-analysis has reviewed the current literature on the prognostic potential of tissue biopsy tumour-associated macrophages; CD163+ TAMs and CD68+ TAMs as well as PD-L1 expression in OSCC." (PMID 37397243, 2023). "Exhaustion markers (PD-1, TIM3, CD39, and FOXP3) and their relationship with tumour-associated macrophages (CD163) were assessed by immunofluorescence on paraffin-embedded samples from n = 43 OE and n = 54 EAOC patients." (PMID 37569458, 2023). "Several studies have found that increased tumor infiltration by CD163-expressing macrophages is associated with shorter OS in patients with PDAC." (PMID 36765852, 2023). "The anti-inflammatory marker CD163 was positively associated with CD8+ T cells in all tumour regions (P < 0.01, in all cases)." (PMID 37324244, 2023). "The Ce6-PDT treatment significantly increased tumor-associated CD163 + M2 macrophage in the ineffective group, pointing out the poor prognosis of the tumor." (PMID 36944686, 2023). "Tumor-associated CD163+ macrophages expressing VCAM1 interacted with tumor-associated erythroid cells expressing ITGA4." (PMID 37894821, 2023). "Inflammatory intratumoral macrophages (high CD68+/CD163+ ratio) and other inflammatory tumor-associated myeloid cells have been associated with improved ICI response." (PMID 37433281, 2023). "In this work, three out of four Pheo/PGL tumours with mutations in genes encoding for the SDH subunits showed the highest levels of CD163 compared with tumours harbouring different mutations." (PMID 37033265, 2023).
tumor (continued). "We noted direct coculturing increased stemness among CSC populations and induced both M1 (CD80 and HLA-DR) and M2 (CD163) tumor associated macrophage polarization." (PMID 37249733, 2023). "Tumor-associated macrophage markers (CD163), tumor-associated fibroblast markers (FAP), and epithelial-mesenchymal transition (EMT) were detected by western blot." (PMID 37907991, 2023). "The MARCO, CD14, FCGR3A, and CD163 genes, which are unique to tumor-associated macrophages (TAMs), were expressed in cluster two." (PMID 38096229, 2023). "The immune microenvironment was characterized by moderate infiltration of M2-like tumor-associated macrophages (TMAs) with positivity of CD163, CSF1R, CD85A (LILRB3), and PD-L1; moderate PD-1 positive T cells, and low FOXP3 regulatory T lymphocytes (Tregs)." (PMID 36975733, 2023). "CD163+ tumor-associated macrophages (TAMs) are a marker of poor prognosis in many types of human cancers." (PMID 37082492, 2023). "Histologically high-grade ‘solid’ tumours were enriched for myeloid cells including tumour-associated neutrophils (TANs), monocytes and CD163+ M2-like macrophages." (PMID 37835491, 2023). "F4/80 (a pan-macrophage marker) and CD163 (an M2 macrophage marker) were used in immunostaining to analyze tumor-associated macrophages." (PMID 36996146, 2023). "This supports the assumption that themajority of tumor-associated macrophages with CD68 positivity are of an M2phenotype also expressing CD163." (PMID 36880147, 2023). "CD163 is a well-known marker for anti-inflammatory macrophages and is usually found in tumor-associated macrophages." (PMID 38140397, 2023). "In early‐stage BC, pulmonary metastasis was associated with increased tumour volume and a higher number of CD163+ macrophages." (PMID 37649158, 2023). "Tumour‐associated macrophages (TAMs), mainly M2 macrophages (marked by CD163), are pivotal players in shaping TME." (PMID 36588094, 2023). "Similar findings were obtained for anti-inflammatory M2 tumor-associated macrophages (TAMs) at the tumor margin based on CD163 staining." (PMID 37928528, 2023). "In future, we will collect more CRC samples to confirm the infiltrations of CD66b+ TANs, Foxp3+ Tregs, and CD163+ TAMs being associated with tumor differentiation." (PMID 37232465, 2023). "CD163 is a scavenger receptor that denotes anti‐inflammatory, chronically inflamed, tumor associated, and wound‐healing M2 macrophage responses, and CD163+ macrophages are found in perifollicular, interfollicular marginal and medullary areas of human LNs." (PMID 36991561, 2023). "CD163 mRNA levels were higher in TAMs from patients with residual tumor mass after surgery and associated with a shorter overall survival." (PMID 37876933, 2023). "The expression of POSTN (R=0.521) and FAP (R=0.606) was correlated with that of CD163 (p<0.001), which is a characteristic gene of tumour-associated macrophages (TAMs)." (PMID 37199594, 2023). "A high occurrence of both the MGL receptor on immunosuppressive CD163+ tumor-associated macrophages and GalNAc-terminated glycans as its ligands has also been demonstrated in glioblastoma patient-derived tumor tissues." (PMID 38069400, 2023). "Tumor-associated macrophages (TAMs) exhibit a CD163+ M2 macrophage phenotype and are abundant in skin lesions of MF." (PMID 37427589, 2023). "Some studies have also found that tumor-associated macrophage-related molecular markers and secreted cytokines, such as CD163, CD206/CD68, and IL-10, were related to the prognosis of HGSOC." (PMID 37124547, 2023). "Tumor-associated macrophages present in the context of malignantly inflamed PDAC are mainly polarized towards a tumor-promoting M2 phenotype (CD163+ or CD204+)." (PMID 37296886, 2023). "P2Y12 expression was confirmed on CD68+ CD163+ tumor-associated macrophages of melanoma in situ where P2Y12 triggers the migration of macrophages towards nucleotide-rich, necrotic tumor areas, and modulates the inflammatory environment upon ADP binding." (PMID 37047682, 2023).
tumor (continued). "CD68+ and CD163+ cells identify macrophages and in line with that also tumor-associated macrophages (TAMs), which are known to be present in high numbers in glioblastomas." (PMID 37543970, 2023). "In summary, we have designed and prepared the CD163 monoclonal antibody modified doxorubicin-polymer prodrug nanoparticles, mAb-CD163-PDNPs, for actively targeting tumor-associated macrophages (TAMs)." (PMID 37111726, 2023). "Given the macrophage plasticity across cancers, we decided to further characterize the functional polarization of FL macrophages utilizing CD163 as a broadly applied marker of tumor-associated myeloid cells." (PMID 37373066, 2023). "Nevertheless, M2 markers, including Cd163, Msr1, and Fcgr1, were highly expressed in Marco4 and Marco6, suggesting their association with tumor progression." (PMID 37697332, 2023). "High CD73 expression was associated with a higher ratio of Foxp3 + /CD8 + tumor-infiltrating lymphocytes (TILs) and CD163 + /CD68 + tumor-associated macrophages (TAMs)." (PMID 36899373, 2023). "Macrophages in the tumor microenvironment, called tumor-associated macrophages, are mostly M2 macrophages with high CD163 expression." (PMID 36983926, 2023). "CD68 isexpressed on the membrane of both M1 and M2 macrophages, and the marker CD163 hasbeen used to identify tumor-associated macrophages (TAM)." (PMID 36880147, 2023). "Next, ccRCC specimens were immunostained for tryptase, CD68, and CD163 to estimate mast cells, total tumor-associated macrophages (TAMs), and M2-TAMs subpopulations, separately." (PMID 36902242, 2023). "Immunostaining of M2-macrophage-specific antigen CD163 was used to detect tumor-associated macrophages, and macrophage infiltration was estimated semi-quantitatively into no/low, moderate, and high infiltration." (PMID 36996051, 2023). "The infiltration of tumor tissue with CD163+ TAMs was associated with a poor prognosis, whereas a high M1-to-M2 macrophage ratio predicted a better prognosis for both OS and PFS." (PMID 37298230, 2023). "The expression of M2 markers, including ARG1, IL10 and CD163 was higher in MADCAM1P270Q-reprogrammed tumor-associated macrophages (TAMs) and MADCAM1D242N-reprogrammed-TAMs, but lower or same in MADCAM1WT-reprogrammed-TAMs compared with control." (PMID 35449126, 2022). "CD163+ tumor-associated macrophages can secrete IL-6 to activate tumor cells JAK2/STAT3, promoting EMT and CTC-mediated metastasis, which is closely related to poor prognosis of patients." (PMID 36568117, 2022). "We compared proportions of CD3+, CD4+, and CD8+ T cells, CD57+ natural killer (NK) cells, CD4+ FOXP3+ regulatory T cells (Tregs), and CD68+ CD163+ M2 tumor-associated macrophages (TAMs) between paired ACC and SCCC samples, respectively." (PMID 36032124, 2022). "We also performed CD34 staining to assess microvessel density, α-SMA staining to label cancer-associated fibroblasts (CAFs), and CD163 staining to label tumor-associated macrophages (TAMs)." (PMID 35928724, 2022). "Infiltration of CD163 positive tumor-associated macrophages (TAM) played important roles in the formation of the distinct TME in UCOGC." (PMID 35733218, 2022). "As per the previous study on macrophage infiltration in CRC, CD163 expression was higher in tumor tissues with high macrophage infiltration and associated with worse prognosis." (PMID 36551651, 2022). "The cluster of differentiation 163 (CD163) protein is a macrophage-specific hemoglobin scavenger receptor used for identification of M2-polarized macrophages among tumor-associated macrophages (TAMs)." (PMID 35567733, 2022). "The immunosuppressive myeloid compartment comprises tumor-associated macrophages (TAMs), including CD163+CD204+ tumor associated macrophages (M2), MDSC (myeloid derived suppressor cells), immature mDCs and pDCs." (PMID 35804867, 2022).
tumor (continued). "CD163+ tumor-associated macrophages (TAMs) represent a pro-tumorigenic fraction of TAMs that can suppress T-cell-mediated antitumor immunity." (PMID 35418199, 2022). "To further examine tumor microenvironment (TME) components of PDM, we studied the infiltration with tumor-associated macrophages (TAMs) via CD163 expression together with the expression of the inhibitory checkpoint receptor ligand PD-L1." (PMID 35740561, 2022). "A histological examination revealed that this population (defined as CD68/CD163+C1Q+TREM2+) was present only in tumor tissues and was significantly associated with post-surgical disease recurrence." (PMID 35746551, 2022). "Other researchers demonstrated that anelevated CD163+ cell content was associated with large tumor size, low tumordifferentiation, and metastases in regional lymph nodes." (PMID 36694901, 2022). "Looking in detail, our data also showed that CD163, a marker for M2-type tumor-associated macrophages (TAMs), displayed moderately elevated expression levels (0.7-fold log2 increase) in the hot tumor group." (PMID 36139700, 2022). "Expression of MGL and its Tn O-glycan ligand has been described in GB human tissues, preferentially associated to tumor infiltrating CD163+ cells." (PMID 35682991, 2022). "CD163+ tumor-associated macrophages (TAMs) are a subtype of M2 macrophages shown to have tumor promoting functions, including the promotion of tumor growth, survival, and metastasis." (PMID 35574025, 2022). "Generally, expression of the M2 marker CD163 is associated with tumor aggressiveness and shorter overall survival in many cancers." (PMID 35525858, 2022). "CD163 has been commonly used as a marker for the M2-like type of tumor-associated macrophages (TAMs), which include a range of diverse cell populations that share an overall immunosuppressive function." (PMID 35663986, 2022). "We identify the existence of osteoclast-like giant cells (OGC) which have high expressions of CD68 and CD163, the biomarkers of tumor-associated macrophages (TAMs)." (PMID 36148946, 2022). "Along with reduced metastasis, we observed reduced infiltration of CD68+CD163+ tumor‐associated macrophages in the omentum of mice injected with HM‐β‐catenin shRNA cells." (PMID 35403834, 2022). "We conducted immunostaining of the tumor-associated macrophage biomarkers CD68/CD163 and double staining for PAS/CD31 in ccRCC human specimens to find that higher TAM infiltration was positively correlated with VM formation." (PMID 35443741, 2022). "Nevertheless, CD163 is also increased in tumor-associated macrophages, a class of inflammatory cells in the microenvironment that is immunosuppressive and supports tumor growth, angiogenesis, and metastasis." (PMID 36605202, 2022). "For GC, an increased density of CD163+macrophages in tumor stroma has been shown to be associated with the activationof the immune response and improved patient survival according to single-factoranalysis." (PMID 36694901, 2022). "In contrast, T cells in brain metastases were much more likely to associate with CD163+pSTAT3– macrophages within tumor (P = 0.009) and at the edge (P = 0.031), and with CD163+pSTAT3+ macrophages within tumor (P = 0.036)." (PMID 35316217, 2022). "We demonstrate by staining serial sections that IL18 was mainly expressed by M1-like (CD68+/CD163-) tumor-associated macrophages (TAM) but also M2-like (CD68+/CD163+) TAMs in our cohort." (PMID 36131941, 2022). "The infiltration of tumor-associated macrophages (TAMs) and increased expression of their associated genes, CD163 and CSF1R, were significantly observed in SHH MBs." (PMID 36358838, 2022). "Meanwhile, in the IHC staining, we observed low levels of CD206, CD163, and Iba1 expression in non-tumor-associated dura." (PMID 35534852, 2022). "Tumor-associated macrophage staining (CD68) of tumor biopsies of nine patients obtained at baseline before local ablation revealed tumor regions with CD163+ cells in all patients." (PMID 36353535, 2022).
tumor (continued). "More precisely, these cancers are highly infiltrated by tumor-associated macrophages (TAMs) whose expression characterized by the CD163 marker is correlated with poor overall survival (OS)." (PMID 35742830, 2022). "This limitation of our study was further highlighted by minor discrepancies based on scRNA-seq data, IHC staining, and IMC staining as within non-tumor-associated dura tissue, a considerable population of CD163+ cells and Iba1+ cells were observed via IMC." (PMID 35534852, 2022). "Conversely, other immunoregulatory genes, such as CD274 (coding for PD-L1), IL1R2 (decoy IL1 receptor), and CD163 (marker of M2 and tumor-associated macrophages) were found to be upregulated at the time of diagnosis." (PMID 36230815, 2022). "At the same time, the unfavorable outcome was associated with profoundly higher CD163+ cells in both tumor clusters and stroma." (PMID 35681497, 2022). "We recently reported that statin use is associated with a reduction in CD68+CD163+ pro-tumourigenic tumour-associated macrophage (TAM) proportions in tumour parenchymal and stromal areas of human lung adenocarcinomas." (PMID 34779486, 2022). "We used anti CD11b and anti CD163 MAbs to evaluate the presence of tumor-associated macrophages in ascites spheroids." (PMID 35055018, 2022). "CD163 was inferior to the other markers in every region of interest, however significant associations of a high CD163 with longer survival (p = 0.012) were still observed in the total stroma area at the tumour centre." (PMID 36114487, 2022). "We found that myeloid cells from two clusters (aMΦ, bMΦ), characterized by the expression of tumor-associated macrophage genes (CD163, CCL4, APOE, and HLA-DRA) were strongly connected to the CD8+ exhausted and CD4+ Th1 T cell clusters." (PMID 35177622, 2022). "Like CAFs, macrophages residing within the TME adopt a characteristic feature of the CD163+CD206+ tumor-associated macrophage (TAM) phenotype (2, 17,)." (PMID 35837091, 2022). "Increased CD163 expression on tumor-associated macrophages (TAMs) correlates with poor clinical outcomes in different malignancies." (PMID 36477408, 2022). "CD68- and CD163-labeled tumor-associated macrophages (TAMs) have both tumor-promoting and antitumor effects on tumors, and they both have significant correlation with prognosis." (PMID 36195882, 2022). "The number of CD163+cells was associated with the presence of metastases and tumor-related death in oral melanocytic tumors (p < 0.05 and p = 0.001, respectively)." (PMID 35937296, 2022). "In liver metastasis a barrier is created around T cells at the epithelium by tumour associated macrophages (defined as CD163+ve) which express programmed cell death ligand 1 (PD-L1) and a reduction in cytotoxic T cells." (PMID 36426854, 2022). "In parallel, approximately 32% of the tumor-associated macrophages (CD68+) showed an M2-polarized subtype (CD163+)." (PMID 36010653, 2022). "CD163 is a marker for scavenger receptor activity and is commonly used to demark pro-tumor type tumor-associated macrophages and monocytes." (PMID 35217711, 2022). "A significant reduction in tumour-associated macrophages (CD68+), including the “pro-tumour” M2 phenotype (CD163+), together with lymphocytes (CD3+) was detected in LLC masses after treatment with both the stilbenes." (PMID 35892684, 2022). "Immunohistochemical straining showed that MCHs expressed CD163, a gene marker for tumor-associated macrophages (TAM2), whereas OGCs and partial mononuclear histiocytic cells express CD68." (PMID 35733218, 2022). "Cluster M0 highly expressed immunosuppressive and angiogenic phenotype-related markers (SLC40A1, NRP1, and CD36) and promote tumor progression associated with markers (CD163 and CD163L1)." (PMID 35265520, 2022). "The SHH subgroup are the most enriched in CD163+ macrophages, suggesting different roles of tumor-associated macrophages in medulloblastoma subgroups." (PMID 35464481, 2022).